BAD (BCL2 associated agonist of cell death)
Diseases named in the same sentence as BAD in open-access papers (continued):
Sharing a sentence is not in itself a finding about the gene and the disease.
Hypoglycemia (1 paper, 2011). A decreased concentration of glucose in the blood. "As for neurohumoral responses to insulin-induced hypoglycemia, diminution of GK and loss of BAD have divergent effects." (PMID 22162752, 2011). "Overall, these results indicate BAD deficiency is associated with impaired counterregulatory responses to insulin-induced hypoglycemia, a clinically relevant glucoprivic threat." (PMID 22162752, 2011). "Moreover, BAD deficiency is associated with impaired glucoprivic feeding, suggesting that its role in adaptive responses to hypoglycemia extends beyond hormonal responses to regulation of feeding behavior." (PMID 22162752, 2011). "Here, we demonstrate that protective hormonal and feeding responses to hypoglycemia are regulated by BAD, a BCL-2 family protein with dual functions in apoptosis and metabolism." (PMID 22162752, 2011). "Further dissection of BAD as a molecular modulator of brain glucose sensing and its potential functional collaboration with other known glucose sensors may uncover novel insights as well as new therapeutic targets for the control of hypoglycemia caused by aggressive insulin therapy." (PMID 22162752, 2011). "Our results suggest that BAD's function in the brain is required for proper hypoglycemia detection and initiation of hormonal and feeding responses to glucoprivation." (PMID 22162752, 2011). "Taken together, these findings indicate that brain-specific acute knockdown of Bad is sufficient to impair detection of hypoglycemia and initiation of hormonal counterregulatory responses and highlight a role for central expression and function of BAD in brain glucose sensing." (PMID 22162752, 2011). "This suggests that BAD's role in the control of hormonal responses to hypoglycemia may be independent of GK." (PMID 22162752, 2011).
invasive carcinoma (1 paper, 2015). A carcinoma that is not confined to the epithelium, and has spread to the surrounding stroma. "In each tissue type examined, the BAD-mediated apoptotic pathway PCA score was higher in the normal tissue than in the corresponding invasive carcinoma samples." (PMID 25653146, 2015).
iron deficiency (1 paper, 2012). "Phosphorylation of the BH3-only protein BAD was the second most impacted process with iron deficiency." (PMID 23110188, 2012).
Liver Disease (1 paper, 2025). "As per ‘A Textbook of Liver Disease, 2018’, AKT phosphorylates numerous proteins, such as the pro-apoptotic protein BAD, leading to its inactivation." (PMID 40699800, 2025).
lymphopenia (1 paper, 2024). Reduction in the number of lymphocytes. "The pathway enrichment of BAD’s activation and translocation to the mitochondria suggests that signaling via the intrinsic pathway may be the mechanism by which clinical FIP causes lymphopenia." (PMID 38257841, 2024).
myopia (1 paper, 2025). "Meanwhile, we also found that the level of the anti-apoptotic gene BCL-2 was up-regulated in the sclera in the LIM group after 2 weeks of myopia induction, whereas the pro-apoptotic gene BAD level was decreased." (PMID 40216914, 2025). "Further, we investigated the changes of PIK3R3, AKT2 and TGF-β1, E-cadherin, COLI, BCL-2, BAD, MMP2, and TIMP2 in the sclera of myopic guinea pigs to explore their effects on the development of myopia after 2- and 4-week myopic induction." (PMID 40216914, 2025). "After myopia induction for 2 and 4 weeks, the expression of PIK3R3, AKT2, BAD, BCL-2, TGF-β1, E-cadherin, COLI, MMP2, and TIMP2 was detected by qPCR." (PMID 40216914, 2025).
nevus (1 paper, 2017). Nevus (or naevus, plural nevi or naevi, from nævus, Latin for "birthmark") is the medical term for sharply circumscribed[1] and chronic lesions of the skin or mucosa. "RhoJ deletion in BRAF mutant melanocytes modulates the expression of the pro-apoptotic protein BAD as well as genes involved in cellular metabolism, impairing nevus formation, cellular transformation, and metastasis." (PMID 28753606, 2017).
ovarian endometriosis (1 paper, 2015). A non-neoplastic disorder characterized by the growth of endometrial tissue in the ovaries. "The expression of the BAD-mediated apoptotic pathway was associated with the development and/or progression of ovarian (n=106, p<0.001), breast (n=185, p<0.0008; n=61, p=0.04), colon (n=22, p<0.001) and endometrial (n=33, p<0.001) cancers, as well as with ovarian endometriosis (n=20, p<0.001)." (PMID 25653146, 2015). "The mean BAD-mediated apoptotic pathway expression score of the normal endometrium samples (n=10) was 5.614 vs. −5.614 in the ovarian endometriosis samples (n=10, P<0.001)." (PMID 25653146, 2015).
pulmonary hypertension (1 paper, 2022). Increased pressure within the pulmonary circulation due to lung or heart disorder. "The key pathogenic features of pulmonary hypertension are endothelial apoptosis and vascular inflammation, which are caused by the down-regulation of Amphiregulin, accompanied by HIF-1a and BAD-mediated up-regulation of the target genes such as RRP1B, PHB2, and NCOA6." (PMID 35732465, 2022).
retinoblastoma (1 paper, 2018). A malignant tumor that originates in the nuclear layer of the retina. "We identified the phosphorylation of BAD in retina and retinoblastoma, showing its prominent role in the survival of retina." (PMID 29914080, 2018). "Particularly, we identified Akt, FOXO1, and BAD to be phosphorylated in retina and retinoblastoma tissues." (PMID 29914080, 2018). "We identified BAD to be hypophosphorylated at Ser118 in retinoblastoma." (PMID 29914080, 2018). "Important mediators of the insulin pathway such as Akt, BCL-2 antagonist of cell death (BAD), FOXO1, and FASN were found to be phosphorylated in both retina and retinoblastoma tissues." (PMID 29914080, 2018).
rhabdomyosarcoma (1 paper, 2011). A rare aggressive malignant mesenchymal neoplasm arising from skeletal muscle. "Activated Akt can activate or deactivate its multiple substrates, including mammalian target of rapamycin (mTOR), bcl-2 family member BAD, transcription factor forkhead homolog 1 in rhabdomyosarcoma (FKHR), Mdm2 protein, glycogen synthase kinase 3 (GSK3) and many others, via its kinase activity." (PMID 22107784, 2011).
sarcoma (1 paper, 2020). A usually aggressive malignant neoplasm of the soft tissue or bone. "Studies have shown that CKI can inhibit mouse sarcoma growth by inhibiting ERK, AKT kinase, and BAD phosphorylation." (PMID 33708106, 2020).
Sepsis (1 paper, 2018). Sepsis is defined as life-threatening organ dysfunction caused by a dysregulated host response to infection. "Under conditions of CLP-induced high-grade sepsis, a significant amount of non-phosphorylated BAD translocated to mitochondria in the liver of WT littermate (~27%, 12 h), even though a similar amount of BAD was simultaneously phosphorylated by IKK at Ser26 (32%, 12 h)." (PMID 29795446, 2018).
squamous carcinoma (1 paper, 2012). "The authors showed that in human squamous carcinoma cells, AF1q downregulation was associated with a doxorubicine-resistant cell phenotype and that AF1q upmodulation caused an increased doxorubicin and γ radiation-induced apoptosis through transactivation of the proapoptotic protein BAD via NF-kB." (PMID 22761939, 2012). "Under the same experimental conditions, we did not observe modulation of the proapoptotic protein BAD, previously shown to be regulated by AF1q in human squamous carcinoma cells." (PMID 22761939, 2012).
thalassemia (1 paper, 2022). An inherited blood disorder characterized by a decreased synthesis of one of the polypeptide chains that form hemoglobin. "Increased cell death was distinctly present only in homozygous β0-thalassemia erythroblasts and associated with the up-regulation of pro-apoptotic (Caspase 9, BAD, and MTCH1) genes and down-regulation of the anti-apoptotic BCL-XL gene." (PMID 36143003, 2022). "The dramatically decreased expression levels of BAD during erythroid maturation were observed in both normal and thalassemia cells, suggesting its role in human erythropoiesis." (PMID 36143003, 2022). "Interestingly, significant down-regulation of anti-apoptotic BCL-XL gene but up-regulation of pro-apoptotic Caspase 9, BAD, and MITCH1 genes was observed on day 12 of homozygous β0-thalassemia cells compared to normal cells." (PMID 36143003, 2022).
cancer (117 papers, 2009 to 2025). A tumor composed of atypical neoplastic, often pleomorphic cells that invade other tissues. "MAPK pathway inhibits the apoptotic pathway through the inactivation of Bcl-2-associated death promoter (BAD) and this allows the activation of Bcl-2 and the resistance of cancer cells to apoptosis." (PMID 35834029, 2022). "S100A10 is involved in various cellular processes, regulates plasminogen activation and has been shown to suppress pro-apoptotic capacity of Bcl-2-associated death protein (BAD), which is suggested to have anti-apoptotic function in cancer cells." (PMID 36230614, 2022). "Using PCA modeling, we evaluated the associations between BAD-mediated apoptotic pathway expression and carcinogenesis using a series of clinico-genomic datasets comprising normal and cancer tissues, including cancers of the breast, colon and endometrium." (PMID 25653146, 2015). "The BAD-mediated apoptotic pathway is thus associated with the development of human cancers likely influenced by the protein levels of pBAD." (PMID 25653146, 2015). "The expression of BAD has been linked to chemoresistance in cancer patients." (PMID 35651606, 2022). "Some of the genes specifically mutated in noncoding regions were identified as highly potent cancer drivers, of which BAD had a mutation hotspot in the 3’UTR, DHODH had a mutation hotspot in the Kozak sequence in the 5’UTR, and CHCHD2 frequently showed mutations in the 5’UTR." (PMID 34900699, 2021). "Furthermore, C-1305 treatment resulted in increased expression of mitochondrial apoptosis markers Bcl-2-associated X apoptosis regulator (BAX) and Bcl-2-associated agonist of cell death (BAD) in cancer cells, when compared to controls and 16HBE14o- cells." (PMID 32252403, 2020). "In addition, knockdown of KLF5 in cancer cells increases their sensitivity to DNA damage and related cell death, which is associated with reduced BAD phosphorylation and downregulation of PIM1." (PMID 23755247, 2013). "Our findings revealed an antagonistic interaction between cisplatin and high-THC cannabis extract, which could be linked to alterations in gene transcription associated with cell death (BCL2, BAD, caspase 10), DNA repair pathways (Rad52), and cancer pathways related to drug resistance." (PMID 38674023, 2024). "In cancer studies, dysregulation of BCL-2 family proteins, including BAD, has been linked to promoting cell survival and tumorigenesis." (PMID 40255989, 2025). "A number of prior studies have suggested that inhibition of BAD phosphorylation sensitizes cancer cells to anticancer agents." (PMID 37117198, 2023). "Their mechanism is to induce endothelial cell proliferation and migration to promote vascular and tumor growth and to reduce cancer cell apoptosis by inhibiting the expression of BAD and caspase–9." (PMID 36452344, 2022). "Specifically, the phosphorylation of human (h)BAD at Ser-75, Ser-99, and Ser-118 is required to promote cancer cell survival." (PMID 34681659, 2021). "Though its role in inhibition of mitochondrial BAX/BAD pathway is well known, our finding is the first to clarify the critical role of mitochondrial HK-II in preventing pyroptosis in cancer cells." (PMID 34108030, 2021). "Due to these mutations, BAD was also classified as being highly mutated in the 3’UTR and as the top most significant potential cancer driver." (PMID 34900699, 2021). "The Bcl-2 agonist of cell death (BAD) is a pro-apoptotic protein, which can be inactivated by its phosphorylation in many cancers, so blocking BAD phosphorylation can promote cell apoptosis." (PMID 34248628, 2021). "Phosphorylation of BAD (pBAD) is required for its heterodimerization with 14-3-3 protein and promotion of cancer cell survival." (PMID 34681659, 2021).
cancer (continued). "In the present study, the investigation of underlying mechanisms revealed that the B. adolescentis is able to trigger apoptosis by upregulation of caspase-8, Fas-R, and BAD gene expression in HT-29 and, Caco-2 cancer cell lines." (PMID 33980239, 2021). "Treatment with B. adolescentis significantly up-regulated the expression level of caspase-8, Fas-R, and BAD genes in HT-29 and Caco-2 cancer cell lines." (PMID 33980239, 2021). "ABT-737 bound BCL2, BCLxL, and BCLw with high affinity, thereby mimicking the action of BH3-only protein BAD, demonstrating the sub-micromolar killing of primary cancer cells and cancer cell lines as well as anti-tumor activity in mouse models." (PMID 33198338, 2020). "Studies found that downregulated p-BAD and BAD in cancer cells promoted tumor invasion and migration." (PMID 31920959, 2019). "In line with this, BAD is differentially expressed in human cancers of the ovary, lung, colon and breast." (PMID 30635657, 2019). "The only gene to have a positive correlation coefficient was BAD, indicating the pro-apoptotic capacity of sFRP4 in cancer metabolism in both the tumours examined." (PMID 29385093, 2018). "One way for sexual hormones to induce cancer is the ability of estradiol to stimulate BAD phosphorylation and prevent apoptosis, which is mediated via MEK/ERK/RPS6KA1 and PI3K and Akt pathways." (PMID 29530003, 2018). "In certain types of cancers, it has been demonstrated that BAD phosphorylation is increased due to the increased activities of upstream kinases, and that inhibition of BAD phosphorylation decreases cancer cell survival." (PMID 26791262, 2016). "We also screened 43 cancer cell lines (excluding tumor samples) from various cancer types and found that 32 of these cell lines (74%) exhibited constitutive K-Ras, p27, BAD, and Bax oligomerization." (PMID 27551498, 2016). "Since Bcl-2 family proteins are critical determinants of cellular apoptosis and survival, we evaluated the role of the BAD-mediated apoptotic pathway as a determinant of cancer development and progression." (PMID 25653146, 2015). "In light of this and the identified differences in BAD-mediated apoptotic pathway expression between normal and cancer tissues, we evaluated differences in BAD phosphorylation between normal and cancer cells." (PMID 25653146, 2015). "But this in vitro finding was challenged with recent reports that phosphorylation of BAD is essential for the survival of cancer stem cells, whereas ectopic expression of a phosphorylation-deficient mutant BAD induced apoptosis in cancer stem cells." (PMID 26398947, 2015). "Compared to the immortalized normal cells, the cancer cell lines showed an increase in the percentage of pBAD relative to the total BAD protein levels." (PMID 25653146, 2015). "In the present study, we explored the role of the BAD-mediated apoptotic pathway in the development and progression of cancer." (PMID 25653146, 2015). "We revealed differences in BAD-mediated apoptotic pathway expression between the normal tissue and cancer samples." (PMID 25653146, 2015). "It has been therefore recognized that displacement of BH3-only proteins from Bcl-2/Bcl-XL or direct activation of BAX or BAD through BH3-mediated interaction is a major molecular mechanism for Gos-induced apoptosis in cancer cells." (PMID 25231749, 2014). "mTOR, a master kinase, plays a critical role in the regulation of tumor cell aggressiveness and cancer metastasis and BAD phosphorylation is an important antiapoptotic mechanism of Akt signaling." (PMID 25243186, 2014). "Although the mechanism by which IPA-3 induces the apoptosis of HCC cells is not completely known, PAK1 has been shown to phosphorylate the anti-apoptotic protein, BAD, to suppress the apoptosis of cancer cells." (PMID 23894351, 2013). "BAD, an important regulator of the cell death machinery, has been reported to contribute to tumorigenesis in several cancers." (PMID 23725574, 2013).